PKD2 (polycystin 2, transient receptor potential cation channel)
Diseases named in the same sentence as PKD2 in open-access papers (continued):
Sharing a sentence is not in itself a finding about the gene and the disease.
gout (continued). "Effects of the interaction between PKD2 and ABCG2 on gout has been studied in Chinese and Japanese male populations, respectively." (PMID 38060535, 2023). "The involved genes were ABCG2, SLC2A9, PKD2, ZNF518B, ALDH2, HECTD4, and MAPKAPK5 in the phenotype of gout; and only gene SLC2A9 was found in the AH phenotype." (PMID 36221101, 2022). "In addition, PKD2 expressed in B cells may be involved in B cell-mediated gout inflammation." (PMID 35922835, 2022). "Our study explored the effect of epistatic interactions between PKD2 and ABCG2 on the progression from elevated serum urate to gout." (PMID 32000861, 2020). "Our results uncover that epistatic interactions between PKD2 and ABCG2 influence all progressions from elevated serum urate to gout." (PMID 32000861, 2020). "The role of lymphocytes related to gout development has been well recognized, but it unclear how ABCG2 interact with PKD2 in the inflammation stage of gout." (PMID 30899057, 2019). "This study confirmed that pairs of rs2728121 in PKD2 and rs1481012 in ABCG2 can impact the etiology of elevated serum urate, hyperuricemia, and gout, which supports the fact that rs1481012 discovered in this study influences gout." (PMID 38060535, 2023). "Interestingly, ABCG2, PKD2, and SPP1 genes were found to be significantly related to gout/AH in all three comparisons (gout vs normal; gout vs AH; AH vs normal)." (PMID 36221101, 2022). "We supposed that PKD2 can indirectly influence the development of gout, by interacting with ABCG2 since no direct role of PKD2 have been identified until now." (PMID 32000861, 2020). "Based on that, PKD2 is commonly not considered as a candidate gene for serum urate and gout." (PMID 32000861, 2020). "Future research into the functional role of PKD2 in lymphocytes may also help explain why not all ADPKD patients develop gout." (PMID 30899057, 2019).
pancreatic cancer (8 papers, 2015 to 2024). "In an attempt to address this issue we found that STK33 overexpression in MIA PaCa2 pancreatic cancer cells was associated with augmented kinase activity and expression of PKD2, another serine/threonine kinase described as a client of HSP90." (PMID 29100402, 2017). "In pancreatic cancer cell lines, PKD2 is known to regulate the secretion of MMP-2, MMP-7 and MMP-9 via a multiprotein complex with ARF1 and ARL1, and Arfaptin2,28,76 aiding the invasion of cells in vitro and in vivo." (PMID 38323010, 2024). "The PKD-2 also mediates production of various angiogenic factors in human pancreatic cancer cells and stimulates the angiogenic response of the host vasculature." (PMID 27200349, 2016). "In another study by the Seufferlein group, PKD2 was upregulated in pancreatic cancer, and ectopic expression of PKD2 significantly enhanced invasion of pancreatic cancer cells in the surrounding three-dimensional ECM through stimulating expression and secretion of MMP-7 and MMP-9." (PMID 33807058, 2021). "Collectively this data suggests that PKD2 plays an essential role in not only IL-35 expression by B cells, but also effector T cell function and ultimately regulates balance of tolerogenic and anti-tumor immunity in pancreatic tumor growth." (PMID 35046933, 2021). "It has also been demonstrated that PKD2 mediates cell invasion through the expression and secretion of MMP-1 in glioblastoma and MMP-7 and MMP-9 in pancreatic cancer." (PMID 39408603, 2024). "PKD2 was a crucial mediator of hypoxia-induced VEGF-A expression and secretion in pancreatic tumor cells and promoted tumor-driven blood vessel formation and tumor growth in vitro and in vivo." (PMID 33807058, 2021). "When investigating such a possibility we found that overexpression of STK33 was paralleled by an augmented PKD2 expression and activity particularly in MIA PaCa2 pancreatic cancer cells as demonstrated by the western blot analysis." (PMID 29100402, 2017). "Notably, the PKD2-and PKD3-regulated secretomes have exhibited pro-invasive and pro-motility properties in prostate and pancreatic cancer." (PMID 38323010, 2024).
polycystic liver disease (8 papers, 2014 to 2025). "Polycystic liver disease (PLD) has been associated with mutations in both the PKD1 and PKD2 genes in patients, and is also observed in genetically engineered mice bearing these mutations." (PMID 25474361, 2014). "Defects in the PKD2 gene cause PKD with or without polycystic liver disease [MIM:613095]." (PMID 41181723, 2025).
glioblastoma (6 papers, 2016 to 2025). The most malignant astrocytic tumor (WHO grade IV). "Subsequently PKD2 was revealed to be related to migration and invasion of glioblastoma cells in vitro in 201324." (PMID 30718593, 2019). "PKD2 is also relevant for the development of glioblastoma multiforme (GBM), since high expression of the kinase has been reported in both low-grade and high-grade human gliomas." (PMID 26848698, 2016). "Besides the regulation at G2–M, PKD2 abrogation could also induce G1 arrest of glioblastoma cells, correlating with the downregulation of cyclin D1." (PMID 33807058, 2021). "Glioblastomas demonstrated the greatest increase in PKD1 and PKD2 expression compared to other grades of malignancy (p < 0.05)." (PMID 40299470, 2025). "PKD2 has also been reported to promote migration and invasion by regulating MMP-1 and integrin expression in glioblastoma." (PMID 33807058, 2021). "However, the expression levels of PKD1 and PKD2 had no influence on the OS or PFS of glioblastoma patients." (PMID 40299470, 2025).
autosomal recessive polycystic kidney disease (5 papers, 2015 to 2022). An inherited disorder characterized by the development of cysts affecting the collecting ducts. "ADPKD is typically a late-onset disease and mainly caused by mutations in PKD1 or PKD2, but about 2–5% of patients show an early and severe phenotype that is clinically often indistinguishable from autosomal recessive polycystic kidney disease (ARPKD)." (PMID 25646624, 2015). "Renal cysts are genetically heterogeneous conditions and both PKD1 and PKD2 genes from dominant form, can be inherited in a recessive way, known as autosomal recessive polycystic kidney disease (ARPKD)." (PMID 36538546, 2022).
intracranial aneurysms (5 papers, 2013 to 2024). "PKD1 and PKD2 patients seem equally likely to develop intracranial aneurysms, while patients with specific mutations of PKD1 are more likely to have vascular complications." (PMID 39628750, 2024). "Vascular abnormalities in ADPKD such as intracranial aneurysms are probably linked to mutations in PKD1 or PKD2, an integral membrane protein involved in cell-cell and cell-matrix interactions." (PMID 25763300, 2015). "Patients with PKD1 and PKD2 seem equally likely to develop intracranial aneurysms, while patients with mutations to the 5' half of PKD1 may more likely have vascular complications." (PMID 24571546, 2014). "The genes responsible, PKD1 and PKD2, respectively, appear to have equivalent expression of intracranial aneurysms and play a direct pathogenetic role in aneurysm formation." (PMID 24571546, 2014).
brain aneurysm (4 papers, 2020 to 2023). A congenital or acquired aneurysm within the cranium. "The causative genes of brain aneurysm were three variants in PKD1, two variants in PKD2, and three variants in other genes." (PMID 36833371, 2023). "Brain aneurysm was observed in eight patients (16%), and the causative genes were PKD1 (missense (n = 2), nonsense (n = 1)), PKD2 (missense (n = 1), splice-site (n = 1)), ZNF423 (missense), GLIS2 (missense) or PKHD1 (missense) or WDR19 (splice-site), and CEP164 (missense)." (PMID 36833371, 2023). "Therefore, as it is denoted in our patient individuals with both PKD2 and NF1 mutations seemed not have a greater risk for tumor and/or cerebral aneurysm formation than expected with either condition alone." (PMID 32533764, 2020).
cholangiocarcinoma (4 papers, 2021 to 2024). A carcinoma that arises from the intrahepatic biliary tree (intrahepatic cholangiocarcinoma) or from the junction, or adjacent to the junction, of the right and left hepatic ducts (hilar cholangiocarcinoma). "In cholangiocarcinoma (CCA) lnc-PKD2–2-3 increased CD44, CD133 and OCT4 expression as well as the CD44 + CD133+ cell proportion, raised tumor sphere forming efficiency and enhanced tharapy resistance to 5-FU in TFK-1 and Huh-28 cells." (PMID 33588867, 2021). "Similarly, the expression of lnc‐PKD2‐2‐3 is positively correlated with CSC markers in cholangiocarcinoma (CCA) and is markedly upregulated in stem‐like cells when compared to normal CCA cells." (PMID 37961996, 2024). "Furthermore, microarray analysis of cholangiocarcinoma and adjacent healthy tissues revealed differential expression of the lncRNA lnc-PKD2-2-3, which was confirmed in 60 paired samples by reverse transcription-quantitative polymerase chain reaction (RT-qPCR)." (PMID 33799834, 2021). "Our previous study observed that long non-coding RNA PKD2-2-3 (lnc-PKD2-2-3) is related to advanced tumor features and worse prognosis in cholangiocarcinoma (CCA)." (PMID 35965521, 2022). "In this study, lnc-PKD2-2-3 was confirmed to promote oncogenic and stem-like characteristics such as poor tumour differentiation, advanced TNM stage, increased carcinoembryonic antigen expression, and was associated with poor overall survival for cholangiocarcinoma patients." (PMID 33799834, 2021). "Indeed, lnc-PKD2-2-3 was upregulated in cholangiocarcinoma stem-like cells." (PMID 33799834, 2021).
colorectal cancer (4 papers, 2020 to 2025). A primary or metastatic malignant neoplasm that affects the colon or rectum. "In colorectal cancer, high PKD1 and PKD2 expressions have been associated with reduced recurrence-free survival and overall survival of the patients." (PMID 40299470, 2025). "Collectively all these results reveal that the RIMKLB gene has a positive association and correlation with AKT3, MPDZ, PKD2, and MAP1B to upregulate the gene expression to induce the development of colorectal cancer." (PMID 35444692, 2022). "Moreover, in vitro data in colorectal cancer demonstrate that both PKD1 and PKD2 promote an epithelial–mesenchymal transition (EMT)." (PMID 40299470, 2025). "A similar expression pattern is also observed in other tumor types: in colorectal cancer (CRC), PKD1 is expressed only in normal colon cells, PKD2 is the dominant isoform at the transcriptional level in tumor samples, and both PKD2 and PKD3 are highly expressed in CRC cell lines." (PMID 37293129, 2023).
diabetes (4 papers, 2015 to 2025). "Accordingly, ablation of PKD2 function was associated with resistance to obesity and diabetes as well as improved microbiota profile in the intestine." (PMID 33949105, 2021). "Moreover, deletion of PKD2 resulted in resistance to high‐fat diet‐induced diabetes and pathological changes in the gut microbiota." (PMID 33949105, 2021). "Importantly, deletion, inactivation, or inhibition of PKD2 ameliorates high‐fat diet‐induced obesity and diabetes and improves gut microbiota profile in mice." (PMID 33949105, 2021). "However, the role of PKD2 in regulating glucose and lipid metabolism and in the development of obesity‐induced diabetes is not known." (PMID 33949105, 2021).
Hydrocephalus (4 papers, 2017 to 2023). Hydrocephalus is an active distension of the ventricular system of the brain resulting from inadequate passage of CSF from its point of production within the cerebral ventricles to its point of absorption into the systemic circulation. "Mechanosensory proteins polycystic kidney disease 1 (Pkd1) and Pkd2 are expressed in primary cilia of RGCs, and their ablation leads to postnatal hydrocephalus and planar cell polarity defects in mouse ventricular epithelium." (PMID 27993979, 2017).
hyperuricemia (4 papers, 2020 to 2023). An abnormally high level of uric acid. "ABCG2 and PKD2 were found to have epistatic interactions, and two SNP pairs (rs2728121:rs1481012 and rs2728121:rs2231137) were mainly identified as associated with the serum urate concentration or risk of hyperuricemia." (PMID 35813212, 2022).
lung carcinoma (4 papers, 2018 to 2023). "For instance, protein kinase D2 (PKD2) is implicated in the angiogenesis, metastasis, and invasion of various malignant tumors (e.g. liver cancer, lung cancer) after being activated." (PMID 38102722, 2023). "miR-106b-5p was reported to be downregulated in non-small cell lung cancer and its forced upregulation increased the sensitivity of lung cancer cells to cisplatin by directly targeting PKD2." (PMID 31986487, 2020). "The survival curve from Kaplan-Meier Plotter database demonstrated that high level of PKD2 predicted poor outcome in lung cancer patients." (PMID 30718593, 2019). "To delineate the domain where the PKD2 promoter interactions are more likely to occur, we used Hi-C data generated from a human lung carcinoma cell line A549 (one of cell lines with highest expression of PKD2)." (PMID 29986647, 2018). "Data from Kaplan-Meier Plotter database and TCGA suggested that high expression of PKD2 might predict poor prognosis and indicate lymph nodes metastasis in lung cancer." (PMID 30718593, 2019). "GSEA, TCGA and K-M plotter database were applied and revealed that high PKD2 expression predicted poor outcome and related with lymph nodes metastasis in lung cancer." (PMID 30718593, 2019).
Bardet-Biedl syndrome (3 papers, 2015 to 2025). A ciliopathy with multisystem involvement. "In one patient (#61), besides a biallelic BBS10 variant, a pathogenic PKD2 variant was identified leading to a double genetic diagnosis (Bardet–Biedl syndrome and ADPKD)." (PMID 39384646, 2025). "For example, PKD2 depends upon the coat complex of Bardet-Biedl Syndrome (BBS) proteins for proper location in the ciliary membrane." (PMID 26230712, 2015).
cardiomyopathy (3 papers, 2016 to 2026). A disease of the heart muscle or myocardium proper. "As the decreased heart function and the biochemical changes in the 9 mo Pkd2+/- mice are suggestive of cardiomyopathy, we examined the gross anatomical features of the mouse hearts." (PMID 27081851, 2016).
gastric cancer (3 papers, 2011 to 2018). A primary or metastatic malignant neoplasm involving the stomach. "Previously we have shown that PKD2 can activate Mef2D in gastric cancer cells via phosphorylation of class II HDACs." (PMID 21298052, 2011). "For example, miR-1271 upregulation enhances cisplatin sensitivity in gastric cancer cells and miR-106b-5p upregulation or PKD2 (polycystin 2, transient receptor potential cation channel) inhibition could increase NSCLC cell sensitivity to cisplatin." (PMID 30175116, 2018). "In a recent report in gastric cancer where low PKD1 and high PKD2 expression were detected in poorly differentiated adenocarcinoma, overexpression of PKD1 had no/minimal effects on tumor cell survival and proliferation, which is consistent with our findings." (PMID 30419840, 2018).
glioma (3 papers, 2019 to 2025). A benign or malignant brain and spinal cord tumor that arises from glial cells (astrocytes, oligodendrocytes, ependymal cells). "The OS rates for PKD2-low patients were significantly higher than those for PKD2-high patients with low-grade gliomas (p < 0.0001)." (PMID 40299470, 2025). "Zhou and collaborators reported that protein kinase D2 (PKD2) upregulation promotes glioma cell proliferation (U251 and U87 cell lines), while its downregulation causes the opposite effects." (PMID 32023813, 2020). "In addition, using public basis data, PKD1 and PKD2 emerged as prognostic factors in low-grade gliomas since the patients with low PKD1 or PKD2 expression display better overall survival compared with the patients with high PKD1 or PKD2 expression." (PMID 40299470, 2025). "PKD1 and PKD2 expression were negatively correlated with the prognosis of glioma patients." (PMID 40299470, 2025). "Besides, Eva Bernhart and his colleges found that RNA‐interference of PKD2 profoundly inhibited growth and changed cell growth of glioma cells." (PMID 30652415, 2019). "To test the possibility of polycystins as a prognostic marker for glioma patients, we analyzed the PKD1 and PKD2 levels in the TCGA-glioma dataset." (PMID 40299470, 2025).
hepatocellular carcinoma (3 papers, 2019 to 2024). A malignant tumor that arises from hepatocytes. "And recently, overexpression of PKD2 was reported in hepatocellular carcinoma (HCC) and was proposed associated with metastasis in HCC22." (PMID 30718593, 2019). "PKD2 expression was found to be upregulated in hepatocellular carcinoma (HCC) and shown to enhance TNF-induced EMT and invasion of HCC cells." (PMID 39408603, 2024). "In addition, PKD2 is upregulated in hepatocellular carcinoma (HCC) and is correlated with the metastasis of HCC." (PMID 33807058, 2021).
Insulin resistance (3 papers, 2018 to 2025). Increased resistance towards insulin, that is, diminished effectiveness of insulin in reducing blood glucose levels. "Here the authors identify a PKD2 mutation that leads to hyperinsulinemia and insulin resistance in Rhesus monkey and show that PKD2 deficiency promotes beta cell insulin secretion by activating L-type Ca2+ channels." (PMID 29789568, 2018). "This discrepancy suggests that global PKD2 deficiency, rather than β-cell-specific PKD inhibition, may be required to influence systemic metabolic outcomes such as obesity and insulin resistance." (PMID 41349796, 2025).
lung adenocarcinoma (3 papers, 2019 to 2024). A carcinoma that arises from the lung and is characterized by the presence of malignant glandular epithelial cells. "Here, we performed this study in order to evaluate the underlying roles and mechanisms of PKD2 in tumorigenesis of lung adenocarcinoma." (PMID 30718593, 2019). "We concluded that high expression of PKD2 was associated with poor prognosis and cancer progression in lung adenocarcinoma patients by promoting EMT." (PMID 30718593, 2019). "Knockdown of PKD2 in lung adenocarcinoma cell lines significantly reduced the expression of mesenchymal markers (N-cadherin, vimentin) and transcription factors (Twist, Snail) that promote EMT; it also inhibited cell migration and invasion." (PMID 39408603, 2024). "were significantly positively correlated with the expression of PKD2 in both A549 and PC9 cells, which indicated that PKD2 promoted EMT in lung adenocarcinoma." (PMID 30718593, 2019). "The mRNA level of PKD2 was significantly elevated in lung adenocarcinoma tissues compared with adjacent tissues (p < 0.05)." (PMID 30718593, 2019). "Herein we evaluated the expression of PKD2 in lung adenocarcinoma and investigated its relationship with EMT." (PMID 30718593, 2019). "Twenty-seven pair of tumors matched with adjacent nontumor tissues were included to investigate the expression of PKD2 in lung adenocarcinoma." (PMID 30718593, 2019). "IHC and qRT-PCR were performed and found PKD2 was elevated in lung adenocarcinoma and negatively related with OS (p = 0.015), PFS (p = 0.006) and the level of E-cadherin (p = 0.021)." (PMID 30718593, 2019). "The role of PKD2 in promoting EMT in lung adenocarcinoma cell lines was next explored." (PMID 30718593, 2019). "Similarly, abrogation of PKD2 induces G2–M arrest in lung adenocarcinoma cell lines." (PMID 33807058, 2021). "However, the mechanism of how PKD2 expression affected prognosis of lung adenocarcinoma patients was still unknown." (PMID 30718593, 2019). "In order to verify the effect of PKD2 in EMT, we also conducted PCR and western blot in lung adenocarcinoma cell lines." (PMID 30718593, 2019). "So we surmised that PKD2 was a positive regulator of EMT, through which high expression of PKD2 contributed to poor prognosis of patients with lung adenocarcinoma." (PMID 30718593, 2019). "Then we collected 27 pair of lung adenocarcinoma tissues for qPCR and 109 tumor samples to perform immunohistochemistry staining, which revealed that PKD2 was high expressed in lung adenocarcinoma and predicted negative outcome for these patients." (PMID 30718593, 2019).